IL4 (interleukin 4)
Diseases named in the same sentence as IL4 in open-access papers (continued):
Sharing a sentence is not in itself a finding about the gene and the disease.
atopic asthma (35 papers, 2004 to 2026). An asthma that is characterized by symptoms that are triggered by an allergic reaction caused by inhaled allergens such as dust mite allergen, pet dander, pollen and mold. "The studied polymorphism of IL-4 has also been associated with different topic disorders like atopic asthma and increased total IgE level." (PMID 34814942, 2021). "Variants of IL-4 and IL-13 have been associated extensively with atopic asthma, serum concentrations of IgE and susceptibility to Crohn's disease." (PMID 18625055, 2008). "A hallmark feature of atopic asthma is the elevation of T helper 2 cytokines, i.e., IL-4 and IL-13." (PMID 29720689, 2018). "Aberrant TSLP, IL-4, and IL-13 levels and activities in the airway lead to the onset and sustaining of atopic asthma and chronic obstructive pulmonary disease (COPD)." (PMID 41294800, 2025). "In this study, we compared changes in serum levels of IL-4 and T1 chemokines and their association with CXCL9 according to the age-related presence of atopic asthma." (PMID 37005469, 2023). "Multiple regression analysis with age as the dependent variable and CXCL9, IL-4, sex, treatment steps, and atopic asthma as explanatory variables revealed that CXCL9 concentrations, IL-4, and atopic asthma were significantly related to age." (PMID 37005469, 2023). "In the present study, serum levels of IL-4 and total IgE and the ratio of atopic asthma tended to decrease with age." (PMID 37005469, 2023). "It is now generally accepted that Th2 cells and Th17 cells significantly contributed to atopic asthma, hence we detected Th2-derived cytokines—IL-4, IL-5, IL-13, and Th17-derived cytokines—IL-17A in BALF." (PMID 33013383, 2020). "IL-4 is classically involved in immunoglobulin class switching for the generation of allergen-specific immunoglobulin E (IgE) and is characteristic of atopic asthma." (PMID 26588780, 2015). "Among them, IL-4 and IL-13-mediated severe atopic asthma with elevated serum IgE and periostin can be treated effectively with an anti-IgE monoclonal antibody, omalizumab, or an anti-IL-13 monoclonal antibody, lebrikizumab." (PMID 25359462, 2014). "In addition, the frequency of circulation Th2 cells that produce both IL-17A and classical Th2 cytokines (IL-4, IL-5, and IL-13) is higher in patients with atopic asthma than healthy controls." (PMID 34344357, 2021). "IL-4 is an important cytokine secreted from T helper type 2 cells; it is responsible for immunoglobulin class-switching, which leads to the production and synthesis of IgE, favoring development of type 2 inflammation and the atopic asthma phenotype." (PMID 31336954, 2019). "Although the immunopathological features of atopic asthma are well characterized as an eosinophilic bronchitis in the airways, with the inflammatory process governed by Th2 cytokines, such as IL-4, IL-5 and IL-13, the immunological and cellular profiles of non-atopic asthma are not well known." (PMID 23253516, 2012). "Atopic asthma is a typical IgE-mediated disease in which the enhanced production of IgE is driven by the activation of Th2 cells, which release a distinct pattern of cytokines, including interleukin 4 (IL4) and IL3, in response to specific antigen presentation." (PMID 23521807, 2013). "The recombinant human IL-4 variant, pitrakinra (Aerovant) competitively inhibits the IL-4Ra receptor complex to interfere with the actions of both IL-4 and IL-13 and initial clinical trials indicated that such an approach may prove beneficial in patients with atopic asthma." (PMID 23189057, 2012). "This case report presents a 35-year-old female with atopic asthma who developed DISR following treatment with Dupilumab, a monoclonal antibody targeting interleukin-4 and interleukin-13." (PMID 42040988, 2026).
atopic asthma (continued). "Eugenol, also detected in Bronchom has also been evaluated for its in-vivo efficacy in a murine model of atopic asthma induced by ovalbumin, wherein it suppressed AHR, eosinophilic influx in BALF and the lungs as well as the release of IL-4 and IL-5." (PMID 39129025, 2024). "The multiple regression models, including sex, atopic asthma, and medication steps, also supported age-related CXCL9 levels induction, IL-4 levels, and the atopic asthma ratio reduction." (PMID 37005469, 2023). "In a mouse model of atopic asthma, pharmacologic activation of PPARG reduces the canonical Th2 cytokines IL4 and IL13 and GATA3 protein in lung extracts." (PMID 24426833, 2014). "In this study intracellular cytokine expression of IL-2, IL-4, IL-10, IL-13, IFN-γ, and TNF-α in CD4+ and CD8+ T cells in children with atopic asthma were measured by flow cytometry." (PMID 21197090, 2010). "Atopic asthma patients with increased TNC basement membrane thickness were also found to have higher eosinophils, T-lymphocytes, macrophages, IL-4+ cells, and anti-IL-5 treatment reduced deposition of TNC in the bronchial subepithelial basement membrane of mild atopic asthmatics." (PMID 36829478, 2023). "Another study in children with atopic asthma showed an increase in the percentage of CD4 and CD8 cells producing IL-4 and a decrease in CD4 cells producing IFNγ in comparison with healthy controls, while the percentage of cells producing TNF remained unchanged." (PMID 27799958, 2016). "In that report, PBMCs of atopic asthma patients carrying −2192C showed increased expression of TLR1 mRNA and protein, increased production of proinflammatory cytokine TNF-α and TH1 cytokines IL-12 and IFN-γ, and decreased production of TH2 cytokine IL-4 after stimulation with TLR1/2 ligand Pam3CSK4." (PMID 27727278, 2016).
myocarditis (34 papers, 2007 to 2026). Myocarditis is a condition that is characterized by inflammation of the heart muscle (myocardium). "Plasma IL4 was identified as a protective factor against myocarditis and also showed associations with endocrine/metabolic diseases." (PMID 40906170, 2025). "IL-2 implicated in myocarditis, and IL-4, IL-6, and IL-13 implicated in fibrosis and cardiomyopathy are the other inflammatory interleukins suppressed by NP-6A4." (PMID 34220518, 2021). "Patients with elevated eosinophilia have been reported to be at higher risk to develop cardiac complications, via IL-4 secretions, driving the progression of myocarditis to inflammatory dilated cardiomyopathy." (PMID 32998408, 2020). "However, IL-4 deficiency exacerbated cardiac inflammation in infectious models of myocarditis induced by Borrelia spirochetes or T. cruzi, which could be due to a compensatory increase in the Th 1 response in these mice." (PMID 32269577, 2020). "While no studies have as yet identified genetic risk biomarkers for the development of myocarditis, cardiac symptoms or troponin release injury post immunization, other adverse events or systemic symptoms have been linked to genetic polymorphism in the cytokine gene for IL4." (PMID 25793705, 2015). "In this regard, eosinophils have been shown to drive myocarditis progression to inflammatory dilated cardiomyopathy (DCMi), and this process is mediated by IL-4." (PMID 37047468, 2023). "TNF-α, IL-6, and IL-17 secretion by B cells promoted Th1 and Th17 differentiation during myocarditis, while the downregulation of IL-4 significantly limited Th2 differentiation." (PMID 37175422, 2023). "The synergistic enrichment of IL-9, IL-3, IL-4, IL-13, and IL-15 during acute myocarditis can be cardioprotective by significantly increasing the number of cardiac helper T cells, shrinking necrotic lesion sizes, and limiting CVB3 genomes." (PMID 37175422, 2023). "Gene ontology analyses identified the upregulation of pathways involved with IL-17, NF-κB, TNF, IL-1β and IL-4 signaling, cell death, and viral life cycle regulators in neutrophils during myocarditis." (PMID 37175422, 2023). "IL-4 deficiency in mice improves heart function during acute CVB3 myocarditis, suggesting that TLR3 prevents myocarditis by reducing viral replication and IL-4 levels in the heart." (PMID 37113698, 2023). "Over 80% of Bcl6−/− mice developed myocarditis, and over 70% of mice suffered from pulmonary vasculitis, with high levels of IL-4, −5, and −13." (PMID 35436984, 2022). "Th2 responses can reduce acute myocarditis by promoting T regulatory (Treg) cells and secreting IL-4 and IL-10." (PMID 35198554, 2022). "Th2 cells and related cytokines like IL-4 and IL-13 are critical in severe myocarditis with eosinophil expansion, and IL-4 is the signature cytokine." (PMID 32269577, 2020). "Over 80% of Bcl6-/- mice exhibit myocarditis and over 70% have pulmonary vasculitis with elevated levels of IL-4,–5, and −13, cytokines known to directly impact liver metabolism." (PMID 30983568, 2019). "Our results open perspectives of IL-4 role in chagasic myocarditis initial events in a more complex frame than the dichotomy Th1/Th2." (PMID 30622430, 2018). "We demonstrate that in early stages of acute phase, IL-4−/− knockout animals presented milder myocarditis with lower IFN-γ production and higher in situ IL-10 production, despite Th1 cells increase in splenocyte general repertoire." (PMID 30622430, 2018). "Our results open perspectives of IL-4 role in initial events of chagasic myocarditis in a more complex frame than the dichotomy Th1/Th2." (PMID 30622430, 2018). "Eosinophil-derived IL-4 is important for chronic disease progression in myocarditis, and IL-22BP blocks protective functions of IL-22 in UC." (PMID 28496445, 2017).
myocarditis (continued). "Since in both EAM models the activation of heart pathogenic T cells is independent of functional TLR4, it is not surprising that C3H/HeJ develop BCG-porcine myosin induced myocarditis after blocking IL-4." (PMID 24586934, 2014). "Although a Th2-type response to CVB3 infection results in reduced acute myocarditis, IL-4 increases chronic heart disease by increasing MC degranulation and fibrosis." (PMID 23675015, 2007). "In mice, while IL-4 plays a critical role in controlling myocarditis and inhibiting Th1 cell responses that produce IFN-γ, it is also implicated in intracellular parasite replication and, notably, in the phosphorylation of STAT6 in cardiac fibroblasts, leading to increased collagen production." (PMID 40391216, 2025). "Additionally, in viral and autoimmune models of myocarditis, females, as they have higher levels of Treg cells and other regulatory factors such as T cell Ig mucin (Tim)-3 and IL-4, exhibit notably lower rates of myocarditis compared to males." (PMID 38464847, 2024). "Moreover, the neutralization of IL-4 in mice led to exacerbations of acute myocarditis, confirming the IL-4-mediated Vγ1 protective mechanism." (PMID 37047468, 2023). "Also, eosinophil-derived IL-4 can drive the progression of myocarditis to inflammatory dilated cardiomyopathy, which is a major cause of heart failure in children and young adults." (PMID 35905078, 2022). "Thus, IL-4 absence in acute phase of experimental infection with T. cruzi Colombian strain reduces myocarditis due to lower IFN-γ production and greater IL-10 production in situ and this pattern is not influenced by splenocyte general repertoire." (PMID 30622430, 2018). "In acute myocarditis triggered by cardiotropic strain of T. cruzi, IL-4 absence implies a general polarization for Th1 in the spleen, but in cardiac tissue, inflammatory balance is significantly regulated by an increase in IL-10, triggering a lower inflammatory infiltrate." (PMID 30622430, 2018). "To confirm that the increased IL-4 and decreased IFN-γ levels that we had observed in the heart of TLR3-deficient mice during acute myocarditis were due to a shift to a classic Th2 response, we examined markers of IL-4-driven alternative activation in the heart by qRT-PCR." (PMID 22013485, 2012). "Thus, in the context of a Th2-driven IL-4 response elevated IL-33 protects the heart from cardiac dysfunction during acute CVB3 myocarditis." (PMID 22013485, 2012). "Additionally, IFN-γ-deficient mice, which have an elevated IL-4/Th2 response, develop severe DCM and HF following CVB3 myocarditis or EAM." (PMID 22013485, 2012). "However, we demonstrated in acute myocarditis triggered by T. cruzi cardiotropic strain that IL-4 absence implies a repertorial polarization for Th1, but in cardiac tissue, inflammatory balance is strongly regulated by an increase in IL-10, triggering a lower inflammatory infiltrate." (PMID 30622430, 2018). "In this study, the pooled AAV9-mediated overexpression of 60 cytokines in a human Coxsackievirus-B3-induced myocarditis mouse model allowed the identification of five cardioprotective interleukins (IL9, IL3, IL4, IL13, and IL15)." (PMID 35508525, 2022). "AAV9-IL9 showed remarkable enrichment over all other interleukins in both Pool 60 and Pool 15, and in combination with IL3, IL4, IL13, and IL15 (Pool 5), significantly improved CVB3-induced myocarditis." (PMID 35508525, 2022). "IL-4/ Th2-type immune response: Female mice develop an IL-4, Th2-type immune response following CVB3 infection with significantly lower myocarditis compared to males." (PMID 23675015, 2007). "Because CD4+ T cells were increased by BPA exposure in drinking water, we examined whether IFNγ, IL-4, and/or IL-17A cytokine levels were altered in the heart during acute CVB3 myocarditis following BPA exposure." (PMID 31551929, 2019).
myocarditis (continued). "So even though it appears as if BL/6 mice have higher levels of IL-4 and IFN-β during acute myocarditis (WT for TRIF−/−) compared to B6.129 mice (WT for TLR3−/−), this may only be an artifact of processing." (PMID 22013485, 2012). "The number of IFN-γ-positive cells was significantly higher than that of IL-4-positive cells (P = 0.02), irrespective of the occurrence of heart failure, indicating that T. cruzi induced myocarditis by eliciting a Th1-like response." (PMID 22811738, 2012). "Although IL-4 increases B cell numbers in the heart of female mice following CVB3 infection, macrophages and neutrophils, which are recruited by IFN-γ, are the predominant infiltrate in the heart during acute myocarditis." (PMID 23675015, 2007). "In our study, IL-4 absence at 21 days of infection did not determine a change in amastigotes nest density in cardiac tissue, using 100 forms of Colombian strain of T. cruzi, a reference strain for chagasic myocarditis studies due to its high heart tropism in Balb/c mice." (PMID 30622430, 2018). "Eosinophils are not essential for myocarditis initiation, but they are fundamental in mediating DCM evolution through IL-4 secretion and a Th2 deviation." (PMID 39768171, 2024).
cutaneous leishmaniasis (33 papers, 2010 to 2025). Leishmaniasis affecting the skin. "However, it is unclear if this IL-4-instruction of type 1 immunity also occurs in CL caused by L. mexicana, since the outcome of cutaneous leishmaniasis often depends on the infecting Leishmania species." (PMID 35154068, 2021). "From the results of DisGeNET, the hub genes IL10, IL6, CXCL8, CSF2, IFNG, IL1B, and TNF were causing Visceral Leishmaniasis; IL10, IL4, CXCL8, IFNG, IL1B and TNF found to cause Cutaneous Leishmaniasis and Urban Cutaneous Leishmaniasis." (PMID 36989283, 2023). "Gamma interferon (IFN-γ) and interleukin 4 (IL-4) are key players both in visceral and in cutaneous leishmaniasis." (PMID 34055669, 2021). "In cutaneous leishmaniasis, IL-4 and IFN-γ cytokines play antagonistic roles, as IFN-γ is capable of activating macrophages that, in turn, will produce reactive species of nitrogen and oxygen and eliminate intracellular amastigote forms." (PMID 33880383, 2021). "In experimental cutaneous leishmaniasis, resistance is associated with IFN-γ production and susceptibility to IL-4." (PMID 33092305, 2020). "Given the pathogenic role of IFN-γ–producing CD8+ T cells, our data suggest that IL-4 promotes cutaneous leishmaniasis pathology by not only promoting Th2 immune responses but also pathogenic CD8+ T cell responses." (PMID 32948646, 2020). "To test the role of IL-4 or IL-13 for the action of PSG during cutaneous leishmaniasis we co-infected WT and IL-4Rα-/- BALB/c mice with a low dose of L. mexicana metacyclics in the presence or absence of PSG." (PMID 29352310, 2018). "Th2 cytokines, namely IL-4 regarding cutaneous leishmaniasis and IL-10 and TGF-β in the case of visceral disease, have been related with disease susceptibility and progression by induction of an M2 macrophage phenotype." (PMID 25368612, 2014). "Apart from IL-10, IL-4 also induces Th2 responses and is particularly involved in the promotion of cutaneous leishmaniasis." (PMID 25368612, 2014). "This is the first report showing the effect of cantharidin on IFN-Υ and IL-4 in cutaneous leishmaniasis." (PMID 25371808, 2014). "Although IL-4 and IL-13 are associated with development of type 2 immune responses in models of cutaneous leishmaniasis, there are many conflicting reports of both IL-4 and IL-13 having opposite roles to play in VL." (PMID 22511870, 2012). "Moreover, IL-4-mediated instruction of DCs during infection appears to be pathogen and strain-specific in the context of L. major and L. mexicana-induced cutaneous leishmaniasis in mice." (PMID 35154068, 2021). "Accordingly, our previous study in CD11ccreIL-4Rα−/lox mice, which have impaired IL-4 receptor alpha (IL-4Rα) expression on CD11c+ cells including DCs, confirmed a protective role for IL-4/IL-13-responsive DCs in replication and dissemination of parasites during cutaneous leishmaniasis." (PMID 32039054, 2019). "IFNγ and IL-4 are the key players involved both in VL and cutaneous leishmaniasis." (PMID 27494323, 2016). "Experimental cutaneous leishmaniasis in genetically inbred mice was the first model which showed a mouse strain-dependent polarization of IL-4 and IFN-γ production by CD4+ T cells correlating with either disease susceptibility or resistance and therefore formed the basis of the Th1 and Th2 paradigm." (PMID 26834705, 2015). "Incorporating exogenous IL-4 as an adjuvant for enhancing strong Th1 responses could therefore be utilised to boost vaccine efficiency against cutaneous Leishmaniasis." (PMID 24204259, 2013). "We have recently documented a significant correlation between IL-4 expression and parasite load in cutaneous leishmaniasis patients suggesting high IL-4 expression may help in parasite survival by suppressing host immune responses at the site of infection." (PMID 20404924, 2010).
cutaneous leishmaniasis (continued). "Unlike the models of murine cutaneous leishmaniasis, in which IL-4 is associated with the Th2 response, in the model of infection by L. donovani there are studies showing that IL-4 does not exacerbate the disease and may in fact act in combating the parasite, which is rather paradoxical." (PMID 28767981, 2017). "The current study aimed to investigate the effect of cantharidin on Cutaneous Leishmaniasis (CL) lesions and IFN-γ and IL-4 patterns in infected BALB/c mice." (PMID 25371808, 2014). "As eosinophils have been identified as a source of early IL-4 production in a model of non-healing cutaneous leishmaniasis, we included SiglecF as an eosinophil marker in our flow-cytometric analyses." (PMID 35894051, 2022). "In this particular model of non-healing cutaneous leishmaniasis, IL-4 released by eosinophils induced a phenotype of alternative (M2-like) activation in dermal macrophages and thereby generated a replication niche for the parasites." (PMID 35894051, 2022). "To identify the source of TSLP during cutaneous leishmaniasis, we sorted CD45+ hematopoietic and CD45- nonhematopoietic cells from the ears of either naïve or infected WT and eoCre: Il4/13f/f mice having a selective deficiency of IL-4/IL-13 in eosinophils." (PMID 38030609, 2023).